RNA5S17 (RNA, 5S ribosomal 17)
Synonyms: RN5S17
Gene: Ribosomal RNA gene on chromosome 1 (228,646,040 to 228,646,158, reverse strand). Ensembl gene ENSG00000200370.
Gene Ontology:
Molecular function: structural constituent of ribosome
Cellular component: ribosome
Homologues: Orthologues: dog 5S_rRNA (100% identical), mouse Gm22109 (100% identical), mouse n-R5s121 (100% identical), rabbit 5S_rRNA (100% identical), rat 5S_rRNA (100% identical), chimpanzee 5S_rRNA (87% identical). Paralogues in human: RNA5S1 (100% identical), RNA5S10 (100% identical), RNA5S11 (100% identical), RNA5S12 (100% identical), RNA5S13 (100% identical), RNA5S14 (100% identical), RNA5S15 (100% identical), RNA5S16 (100% identical), RNA5S2 (100% identical), RNA5S3 (100% identical), RNA5S4 (100% identical), RNA5S5 (100% identical), and 26 more.